MIR519A2 (microRNA 519a-2)
Synonyms: hsa-mir-519a-2; MIRN519A-2; MIRN519A2; mir-519a-2
Gene: MicroRNA gene on chromosome 19 (53,762,344 to 53,762,430, forward strand). Ensembl gene ENSG00000284362.
Gene Ontology:
Biological process: miRNA-mediated post-transcriptional gene silencing
Homologues: Orthologues: chimpanzee ptr-mir-519a (100% identical), macaque mml-mir-517b (87% identical). Paralogues in human: MIR519C (91% identical), MIR522 (91% identical), MIR520C (90% identical), MIR516A1 (89% identical), MIR520F (89% identical), MIR516A2 (87% identical), MIR518E (87% identical), MIR516B1 (86% identical), MIR517A (86% identical), MIR519B (86% identical), MIR523 (86% identical), MIR518C (85% identical), and 12 more.